TAAR1 (trace amine associated receptor 1)
Diseases named in the same sentence as TAAR1 in open-access papers (continued):
Sharing a sentence is not in itself a finding about the gene and the disease.
clear cell carcinomas (1 paper, 2021). "Ovarian clear cell carcinomas with smaller sizes of the primary tumor (pT1, n = 6) had a significantly higher TAAR1 expression (median IRS of 2.5) than clear cell carcinomas with a higher pT status (pT2, n = 3; pT3, n = 1) (median IRS of 0)." (PMID 34445181, 2021).
colitis (1 paper, 2026). Inflammation of the colon. "Treatment with the selective TAAR1 antagonist EPPTB substantially improved colitis symptoms, including reduced weight loss, lower DAI scores, prevention of colon shortening, diminished tissue damage, and decreased expression of pro-inflammatory cytokines (TNF-α, IL-6, and IL-1β) in colonic tissue." (PMID 41550498, 2026). "Pharmacological blockade of TAAR1 with EPPTB significantly attenuates colitis severity by inhibiting trace amine-induced 5-HT signaling, reducing intestinal inflammation, and restoring gut barrier integrity." (PMID 41550498, 2026). "This study aims to evaluate the effects of the TAAR1 antagonist EPPTB in a DSS-induced colitis model, focusing on inflammation, barrier function, and 5-HT signaling, to explore its therapeutic potential." (PMID 41550498, 2026). "•TAAR1 inhibition alleviates colitis severity, intestinal inflammation, and barrier dysfunction." (PMID 41550498, 2026). "We next explored whether TAAR1 inhibition preserves intestinal barrier function in DSS-colitis." (PMID 41550498, 2026). "This study confirms marked elevations in fecal TAAR1-agonist amines (tryptamine, phenethylamine, tyramine) in both UC patients and DSS-induced colitis mice." (PMID 41550498, 2026). "In summary, our study demonstrates that microbiota-derived endogenous TAAR1 agonists Tryp, PEA, and Tyr are elevated in both ulcerative colitis patients and DSS-induced colitis mice." (PMID 41550498, 2026). "Given the detrimental role of 5-HT in IBD and the elevated levels of TAAR1-activating amines (Tryp, PEA, and Tyr) in both UC and DSS-colitis models, we evaluated the therapeutic potential of TAAR1 inhibition in chronic DSS-colitis." (PMID 41550498, 2026). "To further investigate the anti-inflammatory effects of TAAR1 inhibition, we assessed the impact of its antagonist EPPTB on colonic cytokines in DSS-induced colitis mice." (PMID 41550498, 2026).
Dyskinesia (1 paper, 2010). A movement disorder which consists of effects including diminished voluntary movements and the presence of involuntary movements. "Thus, a potential contribution of elevated 3-MT levels to at least some specific manifestations of L-DOPA-induced dyskinesias and the role of TAAR1 in these processes deserve further detailed investigation." (PMID 20976142, 2010).
endothelial dysfunction (1 paper, 2025). In vascular diseases, endothelial dysfunction is a systemic pathological state of the endothelium (the inner lining of blood vessels) and can be broadly defined as an imbalance between vasodilating and vasoconstricting substances produced by (or acting on) the endothelium. "These functional improvements reinforce the notion that TAAR-1 plays a pivotal role in mediating the broader spectrum of endothelial dysfunction observed with METH exposure, including impaired cell motility and compromised junctional integrity." (PMID 40981101, 2025). "We tested whether TAAR-1 mediated endothelial dysfunction induced by METH in RRMECs and cultured OA by using EPPTB, a specific TAAR-1 antagonist." (PMID 40981101, 2025).
familial hypertrophic cardiomyopathy (1 paper, 2016). Hypertrophic cardiomyopathy caused by mutations in the genes encoding components of the sarcomere, in the absence of predisposing conditions. "Recently, D2 mice have been identified as a model of familial hypertrophic cardiomyopathy and these were likely D2 mice that possess the non-functional Taar1 mutation." (PMID 27031617, 2016).
glioblastoma (1 paper, 2017). The most malignant astrocytic tumor (WHO grade IV). "Since autophagy is key for neuronal plasticity, in a second line of experiments we explored whether T1AM and synthetic TAAR1 agonists SG1 and SG2 were able to induce autophagy in human glioblastoma cell lines (U-87MG)." (PMID 29311919, 2017).
Glucose intolerance (1 paper, 2023). Glucose intolerance (GI) can be defined as dysglycemia that comprises both prediabetes and diabetes. "Following this finding, we showed genetic ablation of Taar1 in mice also significantly inhibited the glucose intolerance induced by fecal microbiota from IBS patients with high TyG index and high tryptamine and phenethylamine levels (p < 0.05 in all cases)." (PMID 37591886, 2023).
inflammatory bowel disease (1 paper, 2024). A spectrum of small and large bowel inflammatory diseases of unknown etiology. "TAAR1 mediates both the gastrointestinal and systemic effects of trace amine excess in inflammatory bowel disease." (PMID 39684925, 2024).
lymph node metastases (1 paper, 2021). "Patients diagnosed with ovarian endometrioid carcinoma without local lymph node metastases (pN0, n = 7) had a significantly higher TAAR1 expression (median IRS of 4) than patients with local lymph node metastases (pN1, n = 3) (median IRS of 3)." (PMID 34445181, 2021).
melanoma (1 paper, 2022). A malignant, usually aggressive tumor composed of atypical, neoplastic melanocytes. "Differential expression analysis demonstrated the drastic decrease of TAAR1, TAAR2, TAAR5, TAAR6, and TAAR8 expression in melanomas compared to benign nevi with only TAAR6, TAAR8, and TAAR9 remaining detectable in malignant tumors." (PMID 35053262, 2022). "Essentially undetectable TAAR1, TAAR2, and TAAR5 expression levels were observed in melanoma samples." (PMID 35053262, 2022). "It is notable that, while TAAR1 and TAAR2 expression in melanoma was below the cut-off value, genes involved in the “Olfactory transduction pathway,” coupled with these receptors in nevi were retained in melanoma samples." (PMID 35053262, 2022). "As TAAR1 is coexpressed and heterodimerizes with DRD2, and can manifest its physiological effects in the brain despite its low presence, these receptors may also be prospective therapeutic targets in melanoma." (PMID 35053262, 2022).
narcolepsy-cataplexy (1 paper, 2024). "A clinical study showed that, consistent with TAAR1 agonist suppression of REM sleep in animal studies, the TAAR1 agonist ulotaront reduced daytime sleep onset REM periods and nighttime REM duration in patients with narcolepsy-cataplexy." (PMID 39944134, 2024).
ovarian carcinoma (1 paper, 2021). A malignant neoplasm originating from the surface ovarian epithelium. "The influence of TAAR1 as a positive prognosticator on overall survival indicates a potential prognostic relevance of signal transduction of thyroid hormone derivatives in epithelial ovarian cancer." (PMID 34445181, 2021). "In ovarian cancer cell lines, stimulation of TAAR1 via 3-iodothyronamine (T1AM) reduces cell viability and induces cell death and DNA damage." (PMID 34445181, 2021). "This study shows that high TAAR1 expression is a positive prognosticator for overall survival in ovarian cancer patients and is significantly enhanced in low-grade serous carcinomas compared to high-grade serous carcinomas." (PMID 34445181, 2021). "Aim of this study was to evaluate the prognostic value of TAAR1 on overall survival of ovarian carcinoma patients and the correlation of TAAR1 expression with clinical parameters." (PMID 34445181, 2021). "In this study, we found that membrane, (Spearman rho: 0.342, p = 0.000) as well as cytoplasmic (Spearman rho: 0.299, p = 0.000), TAAR1 expression correlates significantly with ER-α expression in ovarian cancer tissue." (PMID 34445181, 2021). "The influence of TAAR1 on OS in epithelial ovarian cancer patients indicates a potential prognostic relevance of signal transduction of thyroid hormone derivates in ovarian cancer." (PMID 34445181, 2021). "In detail, TAAR1 expression in ovarian epithelial cancer tissue was evaluated, and correlation with overall survival and clinical parameters was performed." (PMID 34445181, 2021). "It is of special interest to evaluate the exact D2R interaction with TAAR1 in ovarian cancer and its influence on tumorigenesis." (PMID 34445181, 2021). "The current study showed that high TAAR1 expression correlates significantly with better OS (p = 0.045) and thus, TAAR1 represents a positive prognosticator for ovarian cancer." (PMID 34445181, 2021). "According to our findings, TAAR1 expression is detectable in the cytoplasm and membrane of ovarian cancer tissue." (PMID 34445181, 2021). "Likewise, the current study showed that general high TAAR1 expression is a positive prognostic factor for OS in ovarian cancer patients (p = 0.045)." (PMID 34445181, 2021). "In this hypothesis generating study, we could observe that TAAR1 was a positive prognosticator for OS in ovarian cancer patients and was expressed significantly higher in low-grade serous carcinoma." (PMID 34445181, 2021). "TAAR1 expression seems to be a positive prognostic factor for OS in ovarian cancer patients." (PMID 34445181, 2021). "Further studies are required to evaluate TAAR1 and its role in the development of ovarian cancer." (PMID 34445181, 2021). "Therefore, TAAR1 could be a novel therapeutic target in ovarian cancer patients." (PMID 34445181, 2021). "Further in vitro studies are required to establish the exact interactions between TAAR1, ER-α and GPER/GPR30 in ovarian cancer." (PMID 34445181, 2021).
ovarian serous carcinoma (1 paper, 2021). "An association between TAAR1 and grading of ovarian serous carcinoma was found, showing that high membrane TAAR1 expression correlates with low-grade ovarian serous carcinoma (p = 0.028)." (PMID 34445181, 2021).
post-traumatic stress disorder (1 paper, 2025). An anxiety disorder precipitated by an experience of intense fear or horror while exposed to a traumatic (especially life-threatening) event. "Building upon this foundation, the present study advances the investigation of TAAR1 agonists in the context of complex post-traumatic stress disorder (CPTSD), a severe condition arising from chronic or repeated trauma exposure." (PMID 41462983, 2025).
Primary hypothyroidism (1 paper, 2018). A type of hypothyroidism that results from a defect in the thyroid gland. "In conclusion, Taar1-deficient mice are hyperthyrotropinemic in the absence of respective signs of primary hypothyroidism such as changes in body weight or TH concentrations in blood serum." (PMID 29615904, 2018). "We conclude that Taar1 deficiency does not lead to primary hypothyroidism, despite the observed changes in the proteolytic network." (PMID 29615904, 2018).
psychostimulant addiction (1 paper, 2016). "Together, these findings demonstrate that TAAR1 agonists are effective at modulating the neurochemical and behavioral effects of psychomotor stimulants and lend strong support to the development of medications targeting TAAR1 as treatments for psychostimulant addiction." (PMID 27092049, 2016).
serous carcinoma (1 paper, 2021). "This is in line with the prognostic value of high TAAR1 expression and low-grade serous carcinoma, both of which are associated with better survival." (PMID 34445181, 2021). "Correlation of membrane TAAR1 expression, with grading of serous carcinoma, showed that TAAR1 is expressed significantly higher in low-grade serous carcinoma (median IRS of 4; n = 22) compared to high-grade serous carcinoma (median IRS of 3; n = 71) (p = 0.028)." (PMID 34445181, 2021).
thyroid (1 paper, 2023). "Thus, it would be interesting to analyze cilia frequencies and lengths in conditions of exposure of Nthy-ori 3-1 cells to 3-iodothyronamine, which is predicted to interact with Taar1 on PC and could thereby affect their maintenance and signaling function in thyroid health and disease." (PMID 37298246, 2023).
psychiatric disorder (22 papers, 2010 to 2025). A disorder characterized by behavioral and/or psychological abnormalities, often accompanied by physical symptoms. "Pathological changes in endogenous TAAR1 agonists, as observed in psychiatric disorders, could underlie alterations in microglial functions." (PMID 37511328, 2023). "The ability to impact the interaction between glutamatergic and dopaminergic circuits may underlie the beneficial behavioral effects of TAAR1 agonists in rodent models of psychiatric disorders." (PMID 34947997, 2021). "Alternatively, pathological changes in endogenous agonists for TAAR1, as seen in psychiatric disorders, could underlie alterations in microglial functions." (PMID 29997511, 2018). "These pieces of evidence suggest that TAAR1 is a new high‐potential target receptor for the treatment of psychiatric disorders." (PMID 38317588, 2024). "These clinically relevant findings may inform future efforts to identify optimal TAAR1 agonists most likely to translate as effective therapeutics for psychiatric disorders." (PMID 40840012, 2025). "TAAR1 knockout (TAAR1-KO) mice display heightened behavioral and neurochemical responses to dopaminergic compounds, presenting TAAR1 as a promising pharmacotherapeutic target for psychiatric disorders." (PMID 39125796, 2024). "TAs of amines are significantly reduced in the brains of patients with various neurologic disorders, which may suggest that the downregulation of TAAR1 function is related to the pathogenesis of psychiatric disorders." (PMID 37153799, 2023). "TAAR1 has been shown to play an important role in modulating monoaminergic neurotransmission, particularly in relation to psychostimulants and addiction, and TAAR1 agonists are increasingly recognized as a novel mechanism for treatment of psychiatric disorders." (PMID 39518904, 2024). "Selective TAAR1 full and partial agonists exhibit similar pro-cognitive, antidepressant- and antipsychotic-like properties in rodents and non-human primates, suggesting TAAR1 as a novel target for the treatment of neurological and psychiatric disorders." (PMID 29456505, 2018).
metabolic disorders (10 papers, 2017 to 2025). "TAAR1 co-localization with insulin in pancreatic β-cells, as well as the modulating effects of TAAR1 on DA transmission, may underlie the relationship between TA-mediated signaling pathways and metabolic diseases, in particular, T2DM." (PMID 38002300, 2023). "When TAAR1 is activated in these organs, it may regulate digestion and food absorption, and insulin is secreted to counteract the metabolic disorders caused by olanzapine." (PMID 35458749, 2022). "It is possible that carriers of these nonfunctional variants could be at higher risk for mental and metabolic disorders, and individuals carrying sub-functional receptors might benefit from treatments with TAAR1 agonists." (PMID 31643000, 2020). "Genetic analysis in patients with psychiatric and metabolic disorders has identified several rare variants in TAAR genes, including TAAR1." (PMID 38237896, 2024). "Pre-clinical animal models have identified TAAR1 as a novel target for metabolic disorders and in regulating immune function." (PMID 34943862, 2021). "The current status of the development of TAAR1 agonists as therapeutic agents for mental and metabolic disorders has been recently summarized in." (PMID 31643000, 2020). "Taar1 has been the preferential target of these investigations, because of its potential role in the pathogenesis of mental and metabolic disorders, which has been extensively reviewed elsewhere." (PMID 31643000, 2020). "Recent evidence indicates that pharmacological TAAR1 activation may offer a novel therapeutic option for the treatment of a wide range of neuropsychiatric and metabolic disorders." (PMID 29311919, 2017). "Thus, the TAARs, at least TAAR1, impact on the metabolic disorders seems to be dualistic." (PMID 38002300, 2023).
cancer (7 papers, 2018 to 2023). A tumor composed of atypical neoplastic, often pleomorphic cells that invade other tissues. "The potent TAAR1 agonist amphetamine has been linked to cancer pathology since at least the 1990s, when daily amphetamine injections were found to increase tumor incidence, growth and metastases in virally-induced cancers on rats." (PMID 29997511, 2018). "TAAR1 is a promising target for the treatment of mental diseases as well as a potential biomarker for cancer prognosis." (PMID 36232383, 2022). "Cancer RNA-seq Nexus datasets with differential TAAR1 RNA expression (adjusted P-value < 0.01) in differential expression analysis." (PMID 29997511, 2018). "Overall, most cancer types displayed median TAAR1 RNA expression levels of zero, which is in agreement with the well-known phenomenon of TAAR1 expression detection being challenging." (PMID 29997511, 2018). "Our analyses show that expression of TAAR1 is modulated in cancers, suggesting that TAAR1 serves a functional role in cancer physiology." (PMID 29997511, 2018). "The expression of TAAR1 in various cancers and its functional significance is an intriguing yet largely unexplored area." (PMID 29997511, 2018). "As both illicit drug use and cancer incidence continue to increase globally it will be imperative to investigate TAAR1 signaling in cancer." (PMID 29997511, 2018). "The current identification of TAAR1 as a marker in numerous cancers, potentially functional and therapeutically targetable, provides a logical direction for future studies on the effects of drugs targeting TAAR1." (PMID 29997511, 2018). "In summary, TAAR1 RNA was present at the lowest levels in cancers of the brain, pancreas, prostate, adrenal gland, stomach and esophagus, sex organs, and B-cells of the blood." (PMID 29997511, 2018). "Reexamining TCGA RNAseq data with respect to the TAAR1 gene revealed varying RNA expression levels across cancer types." (PMID 29997511, 2018). "We provide evidence for a differential pattern of cancer survival based on TAAR1 expression in multiple cancer types." (PMID 29997511, 2018). "Serendipitously during the writing of this review, the first manuscript to posit TAAR1 as a predictor of overall survival in cancer was published." (PMID 29997511, 2018). "This review of current literature and meta-analyses of array-based evidence confirms that TAAR1 is expressed throughout various immune cell types and cancers." (PMID 29997511, 2018). "Here, we review the immunologically-relevant TAAR1 literature and incorporate open-source expression and cancer survival data meta-analyses." (PMID 29997511, 2018). "We mined the NCBI Gene Expression Omnibus (GEO) profiles database which contains gene expression profiles from curated GEO Datasets (GDS) to find evidence of TAAR1 expression across various immune cell types and cancers." (PMID 29997511, 2018). "Further exploration of TAAR1 expression in cancers utilizing the COSMIC database revealed TAAR1 deletions in two cancer cell lines." (PMID 29997511, 2018). "While no data currently exists for TAAR1-specific effects on cancer progression, a literature search for TAAR1 agonists in cancer revealed a small subset of manuscripts describing amphetamine as a tumor-promoter." (PMID 29997511, 2018). "The analyses indicate a potential prognostic value of TAAR1 detection in cancer survival that depends on the cancer type." (PMID 29997511, 2018). "Pharmacologically elucidating TAAR1 signaling in cancer can lead to a better understanding of the mechanisms by which cancer eludes the immune system, and moreover, how drugs of abuse can contribute to cancer development and prognosis." (PMID 29997511, 2018). "The observational data gathered in previous decades linking amphetamine use to cancer progression needs to be revisited in light of the de-orphanization of TAAR1." (PMID 29997511, 2018).